RNU4-44P (RNA, U4 small nuclear 44, pseudogene)
Gene: Small nuclear RNA gene on chromosome X (134,760,208 to 134,760,348, reverse strand). Ensembl gene ENSG00000199920.
Homologues: Orthologues: chimpanzee U4 (100% identical), macaque U4 (96% identical). Paralogues in human: RNU4-13P (89% identical), RNU4-67P (84% identical), RNU4-7P (84% identical), RNU4-23P (83% identical), RNU4-68P (83% identical), RNU4-76P (83% identical), RNU4-16P (82% identical), RNU4-80P (82% identical), RNU4-84P (82% identical), RNU4-31P (82% identical), RNU4-58P (82% identical), RNU4-42P (81% identical), and 81 more.